MSH6 (mutS homolog 6)
Diseases named in the same sentence as MSH6 in open-access papers (continued):
Sharing a sentence is not in itself a finding about the gene and the disease.
Lynch syndrome (continued). "Because of the germline deletion of MSH6 the patient was diagnosed with Lynch syndrome, and colorectal cancer surveillance was recommended from the age of 25 years onwards." (PMID 33811277, 2021). "A 20 bp sequence found to be duplicated in the vicinity of the MSH6 sole canonical PAS in Lynch syndrome patients results in reduced CPA and expression." (PMID 32560344, 2020). "Another study evaluated metachronous colorectal cancer (CRC) incidence according to the MSH6 gene in Lynch Syndrome (LS) patients who underwent a segmental colectomy." (PMID 32746792, 2020). "Digenic inheritance of monoallelic MSH6 and MUTYH variants has been suggested to predispose to Lynch syndrome‐associated cancers." (PMID 32615015, 2020).
Lynch syndrome (continued). "Regarding MMR genes and pituitary tumors, the MSH6 gene was reportedly hypermethylated in pituitary macroadenomas, and a corticotroph pituitary carcinoma developed in a patient with Lynch syndrome." (PMID 32325698, 2020). "Remaining one case was confirmed for loss of MSH6 expression (HC137T), whereas the other for loss of PMS2 (HC8T), both of which were suspected of Lynch syndrome." (PMID 30680068, 2018). "Of the 3 Lynch syndrome patients (MSH6), 2 (66.6%) patients had abnormal findings on their EUS; the first patient had two pancreatic cysts, 3 mm in the head of the pancreas and 4.5 mm in the body, on the first screening." (PMID 30309438, 2018).
Lynch syndrome (continued). "Meanwhile, germline mutations of MSH6 and PMS2 accounts for 7–10% and less than 5% cases of Lynch syndrome respectively." (PMID 28903413, 2017). "Germline mutations in the MMR genes MLH1, MLH2, MSH6, and PMS2 can lead to the development of Lynch syndrome, and heterozygosity for a mutation in one of these genes can result in increased susceptibility to cancer." (PMID 26064726, 2015).
Lynch syndrome (continued). "Lynch Syndrome is a familial autosomal dominant condition characterized by a germline mutation in one of the MMR genes (90% - MLH1 and MLH2, 5-10% MSH6, PMS2)." (PMID 24653752, 2014). "This underlines the importance of EPCAM deletions in the Lynch syndrome, as it is a more frequent cause of LS than mutations in PMS2 or MSH6." (PMID 23938213, 2013). "We have selected three MSH6 VUS that have been found in suspected Lynch syndrome families: hMSH6-P1087R, hMSH6-R1095H and hMSH6-L1354Q." (PMID 24040339, 2013). "Phenotype information for MSH6 and PMS2 mutation carriers is therefore of great interest for the recognition of Lynch syndrome and the formulation of sufficient surveillance schemes." (PMID 20487569, 2010). "Novel MSH6 and PMS2 mutations are being reported and submitted to the current databases for identified Lynch syndrome mutations." (PMID 20487569, 2010). "MSH6 and PMS2 mutations represent 10.3% and 1.9%, respectively, of the pathogenic mutations in our Australian Lynch syndrome families." (PMID 20487569, 2010).
Lynch syndrome (continued). "Lynch syndrome results from germline mutations in DNA mismatch repair (MMR) genes and is associated with a substantially increased lifetime risk of endometrial cancer, reaching up to 71% in carriers of MutS homologue 6 (MSH6) mutations." (PMID 41683729, 2026). "Similarly, isolated MSH6 or PMS2 loss should trigger consideration of genetic counseling and germline testing to identify individuals at risk for Lynch syndrome." (PMID 41462964, 2025). "In case #5, the homozygous MSH6 variant changed the diagnosis from neurofibromatosis to constitutional mismatch repair deficiency (CMMRD), and the family was referred to a clinical geneticist for counseling and surveillance plan for the risk of Lynch syndrome." (PMID 40995433, 2025). "Only one Lynch syndrome patient had MSH6 staining deletion as of yet." (PMID 40018404, 2025).